CLIP3 (CAP-Gly domain containing linker protein 3)
Description:
Functions as a cytoplasmic linker protein. Involved in TGN-endosome dynamics. May modulate the cellular compartmentalization of AKT kinase family and promote its cell membrane localization, thereby playing a role in glucose transport in adipocytes.
Synonyms: CLIPR-59; CLIPR59; RSNL1
Tractability: Antibody: UniProt places it where antibodies can reach, with high confidence; its Gene Ontology location is reachable by antibodies, with high confidence. PROTAC: ubiquitination databases record sites on it.
Gene: Protein-coding gene on chromosome 19 (36,014,660 to 36,033,343, reverse strand). Ensembl gene ENSG00000105270.
Subcellular location: Cell membrane; Cytoplasm; Golgi apparatus, Golgi stack
Pathways (Reactome):
Signal Transduction: Regulation of TNFR1 signaling
Gene Ontology:
Molecular function: ganglioside binding; microtubule binding; protein binding; microtubule plus-end binding
Biological process: membrane biogenesis; negative regulation of microtubule polymerization; peptidyl-L-cysteine S-palmitoylation; positive regulation of apoptotic process; positive regulation of endocytosis; protein transport along microtubule; cytoplasmic microtubule organization; fat cell differentiation; positive regulation of D-glucose transmembrane transport; positive regulation of protein localization to plasma membrane; positive regulation of protein phosphorylation
Cellular component: early endosome membrane; membrane raft; plasma membrane; recycling endosome membrane; trans-Golgi network membrane; cell cortex; cytosol; microtubule plus-end; nucleus; trans-Golgi network; cytoplasm; Golgi stack
Genetic constraint (gnomAD): Loss-of-function variants: 14 observed, 55.09 expected, observed/expected ratio (o/e) 0.25, 90% interval 0.17 to 0.4. The upper end of that interval is the gene's LOEUF score, 0.4, which puts it in group 1 of 6, group 1 being the genes least tolerant of losing a copy. Missense variants: 452 observed, 721.56 expected, observed/expected ratio (o/e) 0.63, 90% interval 0.58 to 0.68. Synonymous variants: 277 observed, 304.54 expected, observed/expected ratio (o/e) 0.91, 90% interval 0.82 to 1.
Homologues: Orthologues: chimpanzee CLIP3 (100% identical), macaque CLIP3 (99% identical), guinea pig CLIP3 (99% identical), dog CLIP3 (99% identical), mouse Clip3 (99% identical), rat Clip3 (99% identical), pig CLIP3 (97% identical), rabbit CLIP3 (83% identical), tropical clawed frog clip3 (78% identical), zebrafish clip3 (78% identical). Paralogues in human: CLIP4 (55% identical), CLIP2 (21% identical), CLIP1 (20% identical), DCTN1 (19% identical).
Diseases named in the same sentence as CLIP3 in open-access papers:
CLIP3 is named in the same sentence as 9 diseases in open-access papers, as found by Europe PMC text mining. Sharing a sentence is not in itself a finding about the gene and the disease. The quoted sentences say what the papers report.
glioma (4 papers, 2021 to 2023). A benign or malignant brain and spinal cord tumor that arises from glial cells (astrocytes, oligodendrocytes, ependymal cells). "CLIP3 functions as a tumor suppressor in gliomas, and its downregulation promotes glioma radioresistance by enhancing stemness." (PMID 37345170, 2023). "Likewise, Spy1 expression was greatly upregulated in GBM patients in comparison to normal brain tissues or low-grade glioma tissues, while CLIP3 expression was highly downregulated in GBM tissues." (PMID 34488821, 2021).
glioblastoma (2 papers, 2021 to 2022). The most malignant astrocytic tumor (WHO grade IV). "In addition, IR in three patient-derived glioblastoma stem cell lines (GSC11, BCL20-HP01, and TS19–176) resulted in similar Spy1 and CLIP3 expression level changes." (PMID 34488821, 2021). "Similarly, in patient-derived GSC11 glioblastoma stem cells, glimepiride significantly increased CLIP3 expression and reduced NANOG and OCT4 expression without IR exposure due to its high intrinsic radioresistance." (PMID 34488821, 2021). "To determine whether Spy1 and CLIP3 directly control glycolytic activity, we tested the oxygen consumption rate (OCR) and ECAR in the GBM cell lines (U87MG and T98G) and patient-derived glioblastoma stem cells (GSC11, BCL20-HP01, and BCL20-HP02)." (PMID 34488821, 2021).
acute lymphoblastic leukemia (1 paper, 2018). Leukemia with an acute onset, characterized by the presence of lymphoblasts in the bone marrow and the peripheral blood. "Some of these genes have already been shown to play a role in hematologic malignancies, including CLL (Pim-2, Met, Rgs16, Ccdc88a, Zcchc18, Clip3), diffuse large B cell lymphoma, follicular lymphoma (Vav3), acute lymphoblastic leukemia (ALL) (Itm2a, Chst1) or acute myeloid leukemia (AML) (Chd3)." (PMID 30271400, 2018).
type 2 diabetes mellitus (1 paper, 2021). A type of diabetes mellitus that is characterized by insulin resistance or desensitization and increased blood glucose levels. "Of the many candidates, glimepiride, which was FDA-approved in 1995 for type 2 diabetes mellitus, significantly increased transcriptional levels of CLIP3." (PMID 34488821, 2021). "Importantly, in combination with IR, glimepiride, an FDA-approved medication used to treat type 2 diabetes mellitus, disrupts GSCs maintenance and suppresses glycolytic activity by restoring CLIP3 function." (PMID 34488821, 2021).
cancer (3 papers, 2021 to 2024). A tumor composed of atypical neoplastic, often pleomorphic cells that invade other tissues. "In turn, a decrease in expression was noted for CYLD and CLIP3 in all cancer grades." (PMID 37233761, 2023). "Given that CSCs have higher glycolytic activity than other cancer cells, and CLIP3 is related to regulation of glucose transmembrane transport, we next examined these functional relationships by measuring the extracellular acidification rate (ECAR) with Seahorse XFp analyzer." (PMID 34488821, 2021). "It was also observed that TNF-α, CASP8, CLIP3, and STAT1 are characteristics of G2 and G3 cancer." (PMID 37233761, 2023).
tumor (1 paper, 2021). "Consistent with the in vitro analysis, expression and nuclear localization of Spy1 were highly increased by IR, and IR/glimepiride combination therapy strongly suppressed tumor growth, but also activated CLIP3 expression, resulting in radiosensitivity." (PMID 34488821, 2021). "Indeed, in limiting dilution assays using U87MG, T98G, and GSC11, we found that the frequency of GSCs capable of forming tumor spheres was decreased by Spy1 knockdown but increased by CLIP3 knockdown." (PMID 34488821, 2021).
CLIP3 also shares sentences with these, for which no sentence is quoted: acute myeloid leukemia (1 paper); diffuse large B-cell lymphoma (1); follicular lymphoma (1).